RAG1 (recombination activating 1)
Diseases named in the same sentence as RAG1 in open-access papers (continued):
Sharing a sentence is not in itself a finding about the gene and the disease.
infection (continued). "Indeed, GF Rag1-/- mice suffered severe body weight loss and succumbed to CR infection by 16–20 dpi." (PMID 39630719, 2024). "Therefore, both B6 mice and genetically modified mice with deficiencies in Rag1, CCR2ko, or Stat1ko were susceptible to MmuPV1 infection." (PMID 38133335, 2023). "As a positive control, Rag1–/– mice were 100% susceptible to the infection." (PMID 36146839, 2022). "infection was studied by comparing T- and B-cell deficient rag1-/- and WT mice." (PMID 34587172, 2021). "Similarly, we observed that Rag1−/− and Rag1−/− x Il17d−/− mice exhibited comparable weight loss and HA expression after infection with influenza A virus with similar viral load in lung." (PMID 31244826, 2019). "Thus, we isolated MHC class II+ lung cells from Erdman-infected, RAG-1-deficient mice 4 weeks post-infection and tested their ability to present Mtb antigens to TB10Rg3 T cells." (PMID 29782535, 2018). "In this work, we show that the rag1−/− genotype that results in deficient adaptive immunity in zebra fish, favored the development of an acquired antiviral alert state that correlated with increased resistance to lethal infection with SVCV." (PMID 28243233, 2017). "From day 4 post-infection through day 6, Rag2−/−Il2rg−/− lost significantly more weight than either Rag1−/−Il7ra−/− or Rag1−/− mice; there was never a difference between weight loss in Rag1−/−Il7ra−/− and Rag1−/− mice." (PMID 28361874, 2017). "Moreover, 100-fold the original infection dose caused a dose response in the body weight of Rag1−/− mice similar to that previously observed in wild-type mice." (PMID 26981777, 2016). "The inability of RB50ΔsigE to cause lethal infections in Rag1−/− mice could be due to failure to enter or survive in the bloodstream and/or systemic organs of these mice." (PMID 22897969, 2012). "RAG1 codes for recombination activating gene 1, which is involved in antibody and T-cell receptor V(D)J recombination and loss of expression leads to abnormalities in T- and B-cell tolerance and immune dysregulation, leading to both an increased risk of infection and autoimmune problems." (PMID 35773312, 2022). "Using a mouse model of S. aureus craniotomy infection, CD4+ T cells were critical for bacterial containment, as treatment of WT animals with anti-CD4 exacerbated infection that was similar to phenotypes in Rag1–/– mice." (PMID 39989461, 2025). "For example, the early window of CD4+ T cell protection that we identified following adoptive transfer in Rag1–/– mice (days –1 to 3 after infection) supports Ag-independent mechanisms given the timescale for induction of Ag-dependent responses." (PMID 39989461, 2025). "Specifically, introducing CD4+ T cells at days –1 or 3 after infection reduced bacterial burdens in Rag1–/– mice, whereas delaying T cell transfer until day 7, when a mature biofilm has formed, was not protective." (PMID 39989461, 2025). "We identified increased viral RNA loads in heart tissue and viremia from Rag1 KO mice, supporting the role of the adaptive immune response during infection." (PMID 40304490, 2025). "Several cytokines (TNF, IL-1β) and chemokines (CXCL10, CCL2, CCL5) were reduced in the brains of Rag1–/– animals at day 14 after infection, which were restored or exceeded WT levels mainly with Th1 adoptive transfer, whereas Th17 cells were less effective." (PMID 39989461, 2025). "Correspondingly, weight gain on an HFD persisted in B6 Rag1-Il2rg double knockout mice, despite infection with S. venezuelensis, and most surrogate genes for type 2 inflammation were reversed." (PMID 40505102, 2025). "Our data support this conclusion, as all NK-sufficient PEP-R619W mice, including immune-competent, Rag1−/−, and α-Iso mice, had significantly reduced liver viral titers at days 3 and 5 post-infection compared to PEP-WT counterpart mice." (PMID 40791464, 2025).
infection (continued). "The importance of adaptive immunity was demonstrated by elevated bacterial burdens in Rag1–/– mice in the brain, s.c. galea, and bone flap with the most dramatic changes evident at day 14 after infection." (PMID 39989461, 2025). "G-MDSC and PMN infiltrates were significantly elevated following CD4+ T cell depletion at day 14 after infection, which recapitulated phenotypes in Rag1–/– mice." (PMID 39989461, 2025). "Consistent with impaired T cell recruitment to sites of infection in Ccr2–/– and Rag1–/– mice, antibody-mediated depletion of CD4+ or CD8+ T cells from WT mice diminished paralysis." (PMID 40459936, 2025). "We showed the myeloid cellular infiltrates in infected lung tissue at Day 14 post-infection of both wild-type and Rag-1-/- mice." (PMID 38198478, 2024). "Since Rag-1-/- mice had significantly increased fungal burden at two-weeks post-infection, we determined if there were differences in cellular recruitment to infected lung tissue in these mice." (PMID 38198478, 2024). "Future studies should test the possibility that mast cell or NK cell activation in the Rag1-/- mouse mediates the subtle tuft cell hyperplasia that occurs after infection with H. diminuta." (PMID 39083533, 2024). "All Rag-1-/- mice succumbed to infection by Day 20 post-infection and the increased mortality was associated with a significant increase in fungal burden at Day 14 post-infection in all organs tested." (PMID 38198478, 2024). "In a gut microbiota-independent manner, CR colonizes in GF Il22-/- and Rag1-/- animals, triggers colonic epithelial tissue damage and systemic dissemination of CR, and results in lethal infections." (PMID 39630719, 2024). "Histopathology demonstrated that diffuse cellular infiltrates were observed in infected lung tissue of C57BL/6 and Rag-1-/- mice at Day 7 post-infection." (PMID 38198478, 2024). "The proportion of mice that cleared the infection increased through 37 dpi when both WT and Rag1–/– had the same percentage of mice sterilizing the infection." (PMID 37865673, 2023). "On day 7 postinfection, LATG135D.OT-I.Rag1–/– CD8 T cells consistently expanded to a greater degree than wild-type OT-I.Rag1–/– CD8 T cells in the Lm-V4 infection settings." (PMID 36914891, 2023). "Firstly, using rag1−/− mice, we conclude that adaptive immunity likely contributes to infection control." (PMID 37882531, 2023). "At five days after CD4+ T cell transfer, respiratory rate was significantly reduced in the C-IRIS group compared with the three control cohorts (naive Rag1−/− mice, Rag1−/− mice with CnH99 infection alone, and Rag1−/− mice with CD4+ T cell transfer alone)." (PMID 37380639, 2023). "Adoptively transferring naïve wild type splenocytes into Rag-1-/- mice allowed peripheral T-cells to be recruited to the MEs in response to infection." (PMID 38125908, 2023). "Taken together, rag1−/− mice are more susceptible to acute UTI, demonstrating a role for adaptive immunity in infection control." (PMID 37882531, 2023). "Previously, we reported that a single dose of immune serum can completely control MCMV infection in infected C57BL/6 Rag1–/– mice for at least 14 days when given at day 3 of infection." (PMID 36719764, 2023). "When infection progressed, up-regulation of the following genes were detected exclusively in isg15 (FC of 0.93), rag1 (FC of 1.21), and perp (FC of 0.6), indicating a change of tendency and slight promotion of antiviral response." (PMID 37346045, 2023). "Rag1-/- (B- and T-lymphocytes deficient) and Rag-γc-/- mice (ILC and B- and T-lymphocytes deficient) were assessed using a similar infection model, and Rag-γc-/- mice developed more severe CDI compared to the WT and Rag1-/- mice." (PMID 36848200, 2023). "At 18 h post‐infection, WT mice and Rag1−/‐ mice showed comparable UPEC burdens in the bladder, whereas ILCs‐deficient Rag2−/−Il2rg−/‐ mice exhibited a significant increase in UPEC burden compared with WT and Rag1−/‐ mice." (PMID 35018740, 2022).
infection (continued). "In contrast to neutrophil and monocyte/macrophage depletion, PopuCATH still provided prophylactic efficacy against E. coli and S. aureus infection in Rag1–/– mice." (PMID 35195067, 2022). "To study the role of intestinal-epithelial LSD1 in response to T. muris, mice were infected with ~200 infective embryonated eggs by oral gavage and we included Rag1-/- mice as a positive control for the infection." (PMID 33788902, 2021). "Rag1-/- mice showed higher levels of parasites in the ME and the choroid plexus compared to WT mice during early infection." (PMID 34587172, 2021). "IFN-γ levels at the site of infection were increased by IL-33 treatment in ILC-sufficient Rag1−/− animals, but were unaffected in Rag2−/−; Il2rg−/− animals." (PMID 33929319, 2021). "We observed parasite and leukocyte invasion of the ME/Arc in both WT and rag1-/- mice early after infection." (PMID 34587172, 2021). "Following FMT, Rag1 heterozygote mice resolve C. difficile while littermate Rag1−/− mice fail to clear the infection." (PMID 33531483, 2021). "Of interest, in addition to Clostridia, Bacteroidota were also expanded in Rag1–/– mice, particularly late in infection, consistent with the failure of Bacteroidota to thrive in the acidic environment generated by the inflammatory response." (PMID 34445184, 2021). "Two weeks post-infection, vaccinated mice of all strains except Rag-1 KO had significantly reduced lung and spleen fungal burdens (p<0.05) compared to unvaccinated control mice." (PMID 35071044, 2021). "Both Rag1–/– and NSG mice were more susceptible to infection compared to wild-type mice at 3 days post infection, as shown by increased fungal burden and more severe histopathology." (PMID 34445184, 2021). "CtD and CtD CT135−/− infection of female RAG1−/− mice resulted in persistent infections; however, the cervicovaginal shedding profiles were distinctly different." (PMID 34526512, 2021). "Whereas male WT mice began to recover on day 7, infected Rag1-/- mice continued to decline and all succumbed to the infection with an MTD of day 9 PI." (PMID 33416494, 2021). "Both immune and metabolic transcripts were elevated in the ME/Arc of WT and rag1-/- mice early after infection, except for ifng mRNA, which levels were only increased in WT mice." (PMID 34587172, 2021). "Female Rag1-/- mice infected with MA-CCHFV began exhibiting significantly greater weight loss than WT mice by day 6 PI and all succumbed to the infection with an MTD of day 7 PI." (PMID 33416494, 2021). "Rag1 KO mice were depleted in vivo of NK1.1+ cells before LVS infection; four days later, splenocytes derived from these mice were then enriched in vitro for CD11c+ cells using magnetic beads." (PMID 32745117, 2020). "There was a significant decrease of pDCs in STAT1/RAG1 DKO mice following infection, the numbers similar to that in infected STAT1 KO mice." (PMID 32310998, 2020). "Consistent with results in WT mice, CHK-265 reduced viremia in Rag1-/- and Ifnar1-/- mice for the first 24 hours post-infection (hpi), and by 48 hpi, both Rag1-/- and Ifnar1-/- mice had high viremia comparable to that in isotype mAb-treated mice." (PMID 32760128, 2020). "Nonetheless, when we depleted Rag1 KO mice of NK cells and then enriched CD11c+ splenocytes four days after infection, amounts of IFN-γ produced by total DC were higher than that typically produced by total splenocytes." (PMID 32745117, 2020). "To address the role of IFNAR signaling specifically in T cells during in vivo infection, we transferred CD4+ cells from Ifnar1-/- or C57BL/6 WT mice to Rag1-deficient mice (Rag1-/- mice)." (PMID 32210480, 2020). "Deep sequencing of total small RNAs showed that in addition to the endogenous miRNAs, Rag1−/− mice produced a typical population of mammalian vsiRNAs in response to the infection with either NoVΔB2 or NoVmB2." (PMID 32753500, 2020).
infection (continued). "That CD4+ T cells alone are sufficient to mediate protection against the infection with R. typhi is further demonstrated by adoptive transfer of immune CD4+ T cells into susceptible T and B cell–deficient C57BL6 RAG1-/- mice." (PMID 33091016, 2020). "To corroborate our ex vivo results which emphasized the importance of SIRT2 inhibition in T cells for restricting intracellular Mtb growth, we performed infection experiments in Rag1-/- mice that lack mature B and T cells." (PMID 32697192, 2020). "RT-qPCR analysis revealed that the IFN-β gene, RIG-I, and ISG15 were all induced by infection with both NoV and NoVΔB2 in C57BL/6 and Rag1−/− mice compared to that with the infection of Stat1/2−/− mice." (PMID 32753500, 2020). "In this work, we conducted a whole-transcriptome analysis of wild-type (WT) and heterozygous rag1 mutant (rag1+/−) zebrafish after infection with the pathogen spring viraemia of carp virus (SVCV)." (PMID 31578442, 2019). "Exclusive lncRNAs expressed after infection in WT and rag1+/− zebrafish were located in the genome to identify neighboring protein-coding genes located within 10 kb upstream and downstream from the lncRNAs." (PMID 31578442, 2019). "We investigated the spatial distribution of ZIKV RNA in the CNS of mice by in situ hybridization (ISH) at peak disease, i.e., day 6 for WT, day 4 for Ifnar1−/−, and day 8 post infection for Rag1−/− mice." (PMID 31511023, 2019). "While viral clearance occurred in WT mice by day 12 post infection (p.i.), Rag1−/− mice continued to show variable levels of viral RNA up to 30 days post infection, suggesting that adaptive immune response is required for timely viral clearance." (PMID 31554802, 2019). "Among these lncRNAs, four were exclusively modulated in WT after SVCV infection, five were exclusively modulated in rag1+/−, and 3 were affected by the infection in both zebrafish lines." (PMID 31578442, 2019). "Weight loss and onset of signs of disease was slightly delayed in Rag1−/− mice compared with WT mice, but all Rag1−/− mice had to be euthanized on day 8 post infection." (PMID 31511023, 2019). "This difference is probably due to a compensatory mechanism present in rag1+/− zebrafish to effectively oppose SVCV infection with an efficient B and T lymphocyte response." (PMID 31578442, 2019). "While lung CFU of wild-type and Rag1−/− mice were comparable, brain CFU were higher in Rag1−/− mice on days 14 and 34 post-infection." (PMID 28837391, 2018). "Infection of (reporter-less) Rag1-/- mice revealed, as expected, an overall reduction of total CD90+ and CD90+IL-17A+ cells due to the absence of TCRβ+ and TCRγδ+ cells." (PMID 29782555, 2018). "We then inoculated naïve wild-type mice with defined doses of spirochetes derived from infected nymphs fed on Rag1 KO mice, as in previous experiments, and monitored infection in recipient mice." (PMID 29621350, 2018). "Remarkably, on day 6 post-infection, 44.9 ± 4.4% of macrophages expressed TCRβ in rag1 knockout mice." (PMID 30044851, 2018). "In another report, IFN blockade by the same monoclonal antibody followed by SC infection with a higher dose of an African lineage strain of ZIKV (Dakar 41519) that was derived from a brain homogenate via passage in Rag1-/- mice resulted in lethal disease." (PMID 28068342, 2017). "Before infection, all of the genes in the sGS except irf3 were upregulated in skin/fins of adult rag1−/− with nklysin and cd8 being the most upregulated." (PMID 28243233, 2017). "In extension, we reconstituted Rag1−/− mice with CD8+ T cells isolated from wild-type BALB/c mice that had cleared CT26 via i.t. infection." (PMID 28637010, 2017). "Infection of adult Rag1-/- mice resulted in the onset of clinical neurological disease within 10–12 dpi in 100% of infected mice, compared to less than 20% of wildtype mice." (PMID 28340587, 2017). "In the conditions used for infection (104 pfu of SVCV per ml, 22°C), both rag1−/− and rag1+/+ larvae were susceptible." (PMID 28243233, 2017).
infection (continued). "The sera were isolated from vaccinated mice, heat-inactivated, sterile-filtered and transferred to Rag1 KO mice (2.7 donor:1 recipient) 3 days before infection." (PMID 29312283, 2017). "Overexpression of activated CASPASE-3 in different tissues before and after infection with SVCV further confirmed increased apoptotic function in rag1−/− zebra fish." (PMID 28243233, 2017). "In sharper contrast with SVCV infection, poly(I:C) injection of rag1+/+ zebra fish, downregulated GS related to complement (columns C and 4), suggesting opposite effects of SVCV and poly(I:C) regarding this pathway." (PMID 28243233, 2017). "Thereafter, bacterial burdens decreased even in the rag1 mutant fish, suggesting that innate immune factors can gradually control infection." (PMID 28934421, 2017). "Through this work, we identified polymorphisms in nsP1 that, when introduced into the RRV-T48 genome, enhanced RRV-T48 sensitivity to type I IFN and attenuated RRV-T48 infection in WT and Rag1-/- mice." (PMID 29244871, 2017). "Later on, 40–45% of adult rag1−/− zebra fish survived infection, while 100% of rag1+/+ died in the first 12 days after infection." (PMID 28243233, 2017). "We then compared the modulated GS after SVCV infection in both genotypes (rag1−/− and rag1+/+) using genotype-matched uninfected zebra fish to calculate differential expression folds." (PMID 28243233, 2017). "On the other hand, SVCV infection of rag1+/+ upregulated complement (columns C and 4), 7TLR7CASP and AMP antimicrobial peptides (columns C) GS." (PMID 28243233, 2017). "C57BL/6 RAG1-/- mice survive the infection with R. conorii as well as with R. typhi for at least 20 days." (PMID 27548618, 2016). "In C57BL/6 RAG1-/- mice, however, R. typhi, re-appears several months after infection and then grows predominantly in the brain." (PMID 27875529, 2016). "Nevertheless, C57BL/6 RAG1-/- mice that lack adaptive immunity survive the infection with R. conorii at least for 20 days which is also true for R. typhi, suggesting that innate immune mechanisms can control the bacteria at least for a certain period of time." (PMID 27875529, 2016). "Expression levels of eMLV env in the spleen, a readout for infection, were as high in all progeny as in the parental virus-carrier Rag1−/− mice and were significantly higher than in uninfected WT mice." (PMID 27647833, 2016). "Experimental infection of recombination activating gene 1 (rag1) gene knockout mice (Rag1−/−), which lack mature B cells or T cells, had higher (2 logs) levels of murine astrovirus (MuAstV) RNA shed in their feces compared to wild type mice at 14 dpi." (PMID 28042824, 2016). "In the present study we show that CD4+ T cells are sufficient to protect against R. typhi in the C57BL/6 RAG1-/- infection model by activating MΦ via IFNγ and other factors." (PMID 27875529, 2016). "Vertical transmission from virus-carrier immunodeficient Rag1−/− mice led to efficient infection of the thymi of immunocompetent WT progeny (Rag1−/− → WT), which would affect thymic selection of RARV2-specific T cells." (PMID 27647833, 2016). "Histopathology analysis of H&E sections prepared at day 14 post-infection demonstrated an equal or greater degree of inflammation in the vaginal lumen and epithelium of Rag1−/− mice infected with M28 GAS compared with WT mice controls." (PMID 27241677, 2016). "C57BL/6 RAG1-/- CD8+ T cell recipients eliminated R. typhi very quickly from the brain as well as from other organs in established R. typhi-infection in C57BL/6 RAG1-/- mice." (PMID 27875529, 2016). "CD8+ and CD4+ T immune cells were obtained from C57BL/6 wild-type mice on day 21 post R. typhi infection and first transferred into C57BL/6 RAG1-/- mice either on day 45 or on day 55 post infection." (PMID 27875529, 2016).